LAG3 (lymphocyte activating 3)
Diseases named in the same sentence as LAG3 in open-access papers (continued):
Sharing a sentence is not in itself a finding about the gene and the disease.
melanoma (continued). "Diagnostic tissues collected from melanoma patients were evaluated using immunohistochemistry for CD163, PD-1, and LAG-3 expression." (PMID 32756500, 2020). "High levels of LAG3 have been described on immunosuppressive Tregs in cancer and specifically in melanoma." (PMID 32861198, 2020). "Functional analyses in melanoma cell lines and correlation of LAG3 methylation data with clinicopathological and immunological features substantiate our findings." (PMID 32861198, 2020). "The expression of immune checkpoint molecules PD-1 and LAG-3 positively correlated with the M2-TAM density in melanoma tissue." (PMID 32756500, 2020). "Doing this, we tested LAG3 methylation as a prognostic biomarker and as a predictive biomarker for response to immune checkpoint blockade in melanoma." (PMID 32861198, 2020). "We performed an independent comparison of LAG3 methylation in melanocytes, melanoma cell lines, and isolated leukocyte subsets from peripheral blood." (PMID 32861198, 2020). "We therefore investigated LAG3 mRNA expression and the influence of the hypomethylating agent 5-azacytidine on LAG3 in the melanoma cell line A375." (PMID 32861198, 2020). "The combination of GSK-3 SMI with anti-LAG-3 therapy significantly decreased tumor growth and, in addition, further inhibited pulmonary metastasis of melanoma cells, more than either agent alone." (PMID 32526891, 2020). "Our results give insight in the tumor cell-intrinsic transcriptional regulation of LAG3 in melanoma." (PMID 32861198, 2020). "With regard to the demonstrated function of LAG3 as a surrogate biomarker for a cytotoxic anti-tumor response, we assumed LAG3 to be predictive for outcome in melanoma patients." (PMID 32861198, 2020). "Concurrent high expression of both CD163 and PD-1 (CD163highPD-1high) or LAG-3 (CD163highLAG-3high) in melanoma were independent poor prognostic factors." (PMID 32756500, 2020). "We detected basal LAG3 mRNA expression in the melanoma cell A375 and an interferon-γ inducible expression after demethylation with 5-azacytidine." (PMID 32861198, 2020). "MHC-II is a ligand of the inhibitory checkpoint receptor LAG3, which is substantially expressed on melanoma-infiltrating T cells." (PMID 31703604, 2019). "A similar effect was observed in models of colon adenocarcinoma, fibrosarcoma, ovarian tumors, melanomas, lymphomas, and multiple myelomas, where the mice were treated with one antibody or with combination targeting LAG-3/PD-1 compounds." (PMID 31717326, 2019). "LAG3 was also shown to be highly expressed on Tregs in the peripheral blood, metastatic lymph nodes and tumor tissues from melanoma and colorectal carcinoma, head and neck squamous cell carcinoma and non-small cell lung cancer patients." (PMID 31434339, 2019). "The human IgG4 monoclonal LAG-3 antibody relatlimab is in late phase clinical trials in combination with nivolumab versus nivolumab monotherapy for first line advanced melanoma treatment." (PMID 30941125, 2019). "Murine studies have indicated that combined use of anti-LAG-3 and anti-PD-L1 in melanoma treatment overcame the requirement for tumor specific T-reg depletion." (PMID 30941125, 2019). "LAG3 is now being tested in clinical trials of patients previously treated with anti-PD-1/PD-L1 agents and preliminary data from melanoma patients has shown efficacy of this dual blockade." (PMID 31434339, 2019). "In vivo, Nrp-1+PD-1hi CD8+ tumour-infiltrating lymphocytes (TIL) in B16F10 melanoma are enriched for tumour-reactive T cells exhibiting an exhausted state, expressing Tim-3, LAG-3 and CTLA-4 inhibitory receptors." (PMID 31350404, 2019). "In melanoma, LAG-3, frequently co-expressed with PD-1 was demonstrated on CD8+ tumor-infiltrating lymphocytes (TILs), leading to their clonal exhaustion and promotion of tumor growth." (PMID 31554169, 2019).
melanoma (continued). "Early data from the anti-LAG3 relatlimab used as simultaneous dual blockade targeting PD-1 together with LAG3 produced an objective response rate of 11% in melanoma patients progressing after anti-PD-1/PD-L1 monotherapy." (PMID 31434339, 2019). "LSECtin, expressed on melanoma is a type II transmembrane protein which belongs to the C-type lectin receptor superfamily and has been identified as a ligand of LAG-3." (PMID 32039024, 2019). "Preclinical studies have shown that, as a result of persistent melanoma antigen expression, LAG-3 expression on TILs is increased, thereby inhibiting T cell action and reducing IFN-γ production within the TME under the influence of PD-1 co-stimulation." (PMID 30941125, 2019). "ERK1/2-dependent pathways up-regulate ICP ligands, such as lymphocyte-activation gene 3 (LAG-3) in melanoma, and PD-1L in malignant pleural mesothelioma, non small cell lung cancer, breast cancer, prostate cancer, bladder cancer, and multiple myeloma." (PMID 31117237, 2019). "Dual blockade of LAG3 and PD-1 pathway demonstrated significant therapeutic synergy for the treatment of melanoma patients from the latest clinical studies." (PMID 30400822, 2018). "The combination of PD-1 and CTLA-4 blockade has demonstrated higher response rates in advanced melanoma, while combination with LAG3 blockade are still carrying on clinical trials (NCT03250832, NCT02658981, NCT01968109, NCT03005782)." (PMID 30607140, 2018). "Co-expression of LAG3 and PD-1 on tumor-infiltrating T cells is found in many human cancers including ovarian cancer, melanoma, hepatocellular carcinoma (HCC) and colon cancer." (PMID 30400822, 2018). "Anti-LAG-3 mAbs or LAG-3 fusion proteins are being tested in melanoma patients resistant to anti-PD-1/PD-L1 ICB as single agent (NCT01968109), or in combination to anti-PD-1 (NCT02676869)." (PMID 30108594, 2018). "LAG-3 is highly expressed in tumor- infiltrating lymphocytes in patients with fibrosarcoma, colorectal cancer, and melanoma." (PMID 30366424, 2018). "Over-expression of LAG-3 in T cells can protect MHC-II-expressing melanoma cells from drug-induced or FAS-mediated apoptosis through MAPK/ERK and PI3K/AKT survival pathways." (PMID 30603054, 2018). "Recently, first data was published from an ongoing clinical trial (NCT01968109), in which anti-LAG-3 in combination with anti-PD-1 showed activity in melanoma patients who were relapsed or refractory to anti-PD-1/-PD-L1 therapy." (PMID 29535740, 2018). "LSECtin, a cell surface lectin of the DC-SIGN family, has been identified as an alternative ligand for LAG-3, and LAG-3 blockade has been shown to result in abrogation of immunoinhibitory effects of LSECtin in a melanoma mouse model." (PMID 29535740, 2018). "In particular, combination therapy of anti-LAG-3 (BMS-986016) plus anti-PD-1 (nivolumab) has shown impressive clinical efficacy in melanoma patients who are resistant to anti-PD-1/PD-L1 therapy." (PMID 30603054, 2018). "In melanoma patient samples, LAG-3 is highly expressed on tumor-infiltrating pDCs, contributing to directing an immune-suppressive environment." (PMID 30603054, 2018). "Only melanoma-infiltrating, tumor-specific T lymphocytes (TILs) upregulated PD-1, LAG-3, and TIM-3 and showed reduced TNF-α, IFN-γ, and IL-2 secretion ability when compared with virus-specific cells." (PMID 30108594, 2018). "LAG-3 is substantially expressed on melanoma TILs, including those with potent immunosuppressive activity." (PMID 28970830, 2017). "MHC II molecules on melanoma cells bind to lymphocyte-activated gene 3 (LAG3) expressed on the surface of pDCs, resulting in their tolerogenic activation." (PMID 29085361, 2017). "A population of expanded CD4+CD25highFoxp3+ Tregs expressing LAG-3 has been identified in the peripheral blood, in T cells of tumor-invaded lymph nodes and in T cells infiltrating the visceral metastasis of melanoma and sarcoma patients." (PMID 28404974, 2017).
melanoma (continued). "On Melan-A specific CD8+ T cells isolated from melanoma patients, LAG-3 is highly co-expressed with PD-1 and TIM-3." (PMID 28404974, 2017). "CD4+TIM3+ was increased from 12% (naïve lymph nodes) to 19% (draining lymph node), other IRs phenotype such as CD4+BTLA+ (38%), CD4+2B4+ (35%), CD4+LAG3+ (27%) was also increased in draining lymph node of melanoma-bearing mice than naïve mice." (PMID 27447564, 2016). "To confirm the T cell exhaustion in cancer, we first examined the expression of IRs such as PD1, TIM3, BTLA, 2B4 and LAG3 in T cells isolated from mice borne with B16F10 murine melanoma." (PMID 27447564, 2016). "Further implying a role for anti-LAG-3 and anti-PD-1 combination therapy, a recent study on banked melanoma tumor samples showed the LAG-3 gene to be overexpressed in PD-L1 positive tumors." (PMID 26850630, 2016). "Melanoma-infiltrating T cells express the lymphocyte activation gene 3 (LAG-3), which is a natural ligand for MHC II." (PMID 22046194, 2011). "Therefore, the combination of LAG-3/PD-1 blockade and chemotherapy demonstrated promising efficacy, notably in treatment-naïve mucosal melanoma with liver metastases." (PMID 41782961, 2026). "Similarly, the combination of relatlimab (an anti-LAG-3 agent) with nivolumab (an anti-PD-1 agent) has shown enhanced therapeutic benefits in patients with advanced melanoma." (PMID 41486149, 2026). "In the subgroup analysis, a benefit of mPFS was also observed in dual inhibition of LAG‐3 and PD‐1 over PD‐1 alone in BRAFmut melanoma, and the NRAS mutation status has not been revealed." (PMID 41492362, 2026). "Previous analysis in advanced melanoma revealed that response to nivolumab plus relatlimab, but not nivolumab, was associated with an on-treatment increase in LAG-3+ T cells." (PMID 41109920, 2025). "This case describes a person treated with the Lymphocyte-activation gene 3 (LAG-3) inhibitor relatlimab and the Programmed cell death protein 1 (PD-1) inhibitor nivolumab for stage IV melanoma who subsequently developed four distinct and significant toxicities." (PMID 41476983, 2025). "Notably, although LAG3 is recognized as an immune checkpoint in melanoma and lung cancer, we demonstrated by cell function experiments that LAG3 inhibited the proliferation of cervical cancer cells." (PMID 41025546, 2025). "LAG-3–blocking Abs have shown efficacy in humans with advanced melanoma." (PMID 40762981, 2025). "Dual checkpoint blockade with nivolumab and relatlimab (anti-PD-1 + anti-LAG-3) has demonstrated significant antitumor efficacy in melanoma, as established in the RELATIVITY-047 trial and subsequent reviews, but may potentiate complex cutaneous toxicity." (PMID 41458837, 2025). "Indeed, we observed an accumulation of FoxP3+ iNKTreg cells within melanoma tumors, a disturbed NCR/NKG2 profile, and a skewed ICP expression toward LAG3, CTLA4, and TIM3, which were associated with early relapse and shorter survival." (PMID 41562072, 2025). "The efficacy and safety profile observed suggest that development of dual PD-1/LAG-3 targeting strategies may still be warranted in selected indications, particularly melanoma, where LAG-3 biology may be uniquely relevant." (PMID 40993242, 2025). "Although TIM-3 and LAG-3 are promising clinical markers, it also seems important to expand research in the use of these molecules in the treatment of ovarian cancer, as is carried out in breast cancer or melanoma." (PMID 40649775, 2025). "Recently, Opdualag, a fixed-dose combination of anti-LAG-3 and anti-PD-1, has shown significant therapeutic efficacy and was approved for treating melanoma in adults and children, marking LAG-3 as the third immune checkpoint pathway approved for clinical use by the FDA." (PMID 40682400, 2025). "In melanoma, immune aging is associated with decreased clonal diversity of tumor‐infiltrating CD8+ T cells and increased expression of exhaustion markers such as PD‐1, LAG‐3, and TIM‐3." (PMID 40926366, 2025).
melanoma (continued). "Consequently, dual inhibition of LAG-3 and PD-1 has demonstrated significant improvements in the clinical outcomes of melanoma." (PMID 39751894, 2025). "Altogether, these observations suggest that iNKT cells are skewed mostly in the tumors of melanoma patients toward a modulated phenotype associated with poorer clinical outcomes, with LAG3 being a critical negative prognostic factor for clinical evolution." (PMID 41562072, 2025). "recently examined the effects of LAG-3 and PD-1 inhibition in patients with advanced melanoma." (PMID 39660130, 2024). "Moreover, we examined the correlation between CTHRC1 expression and immunotherapy markers, including CD274, PDCD1, CTLA4, and LAG3 in colon cancer, thyroid cancer, and melanoma." (PMID 39052013, 2024). "Moreover, NK cells with MAP4K1 expression exhibited significantly increased exhaustion signature (PDCD1, TIGIT, HAVCR2, and LAG3) in melanoma tissues (GSE120575 and GSE72056)." (PMID 38828677, 2024). "LAG-3 has emerged as a pivotal mediator of immunosuppression in melanoma, interacting with MHC-II molecules within the tumor microenvironment (TME) to induce tolerogenic plasmacytoid dendritic cells (pDCs) independently of Toll-like receptors (TLRs), thus sustaining an immunosuppressive milieu." (PMID 39743998, 2024). "In an in vitro study of B16 melanoma cells, the binding of LAG-3 to LSECtin suppressed IFN-γ production and weakened the specific immune response against tumors, an effect that could be reversed by LAG-3 blockade." (PMID 39743998, 2024). "It has been shown that anti-LAG-3 responders typically have >1% LAG-3+ TILs, which could explain a more robust therapeutic effect in melanoma." (PMID 39346924, 2024). "Various mechanisms of blocking LAG-3 function are currently being assessed in clinical trials, including relatlimab, a monoclonal antibody used to treat patients with metastatic or unresectable melanoma." (PMID 38256021, 2024). "Heightened efficacy of combined CPMV IIT and anti-Lymphocyte-activation gene-3 (LAG-3) treatment in a mouse model of melanoma have been observed wherein LAG-3 functions as a next-generation inhibitory immune checkpoint with broad expression across multiple immune cell subsets." (PMID 39851281, 2024). "A study in melanoma patients showed that relatlimab (anti-LAG-3 mAb) plus nivolumab (anti-PD-1 mAb) led to a higher occurrence of adverse events (81.1% vs. 69.9%) and grade 3–4 irAEs (18.9% vs. 9.7%) compared to nivolumab (anti-PD-1 mAb) alone, with a notable rise in hepatitis cases (3.9% vs. 1.1%)." (PMID 38375475, 2024). "Studies have shown that LAG-3 is upregulated in PD-L1–positive melanoma, which could contribute to immunotherapy resistance." (PMID 39534873, 2024). "LAG-3 expression in B16F10 melanomas upon following intratumoral CPMV treatment was examined." (PMID 38349406, 2024). "This combinatory approach has shown promise in preclinical models and early-phase clinical trials, suggesting that LAG-3 inhibitors may provide a complementary mechanism to enhance the effectiveness of existing ICIs in treating melanoma and other cancers." (PMID 39743998, 2024). "With the recent approval of anti-LAG-3 ICIs for the treatment of metastatic melanoma, a better understanding of the role of the melanoma TME and mechanisms mediating patient response to anti-PD-1 monotherapy compared to combination therapy with anti-CTLA-4 or LAG-3, is clearly needed." (PMID 38217840, 2024). "In addition, LAG-3 mRNA expression in melanoma patients is thought to be correlated with tumor progression, and high levels of LAG-3 tend to represent poor DFS and OS." (PMID 39660130, 2024). "In a global phase I/II clinical trial involving LAG3 in untreated advanced melanoma, patients treated with anti-LAG3 in combination with anti-PD-1 exhibited a median progression-free survival of 10.1 months compared to 4.6 months in an anti-PD1-only treatment group." (PMID 39409893, 2024).
melanoma (continued). "Hence, relieving the blocks of proliferation and effector function, explain the beneficial effect of simultaneous targeting of both PD-1 and LAG-3 by combined nivolumab and relatlimab checkpoint blockade therapy in melanoma." (PMID 39424778, 2024). "Additionally, a Phase II clinical trial (NCT03484923) evaluating the efficacy of Ieramlimab combined with Spartalizumab in patients with PD-1 inhibitor-resistant melanoma indicated promising antitumor effects against LAG3-positive metastatic melanoma." (PMID 39743998, 2024). "Notably, the interaction of LAG-3 with LSECtin, expressed in melanoma cells, leads to the inhibition of IFN-γ secretion by effector T cells, while GAL-3, another potential ligand, suppresses CD8+ T cells and DCs." (PMID 39684559, 2024). "Moreover, we summarize the current state of clinical investigation of LAG-3 targeting molecules in melanoma and discuss the position of dual checkpoint inhibition with anti-LAG-3 plus anti-PD-1 antibodies in the arsenal of current melanoma therapies." (PMID 37004702, 2023). "Current therapeutic options in advanced melanoma include PD-1 inhibitors associated or not with CTLA-4 or lymphocyte-activating gene (LAG)-3 inhibitors and in cases of BRAF V600E/K mutated BRAF inhibitors, called targeted therapy." (PMID 37569757, 2023). "We then used single cell RNA-sequencing (scRNAseq) of circulating immune cells from a clinical trial cohort of melanoma patients treated with immune checkpoint inhibitors (ICI) to explore the potential relationship between LAG-3-expressing cells and clinical outcomes." (PMID 37795090, 2023). "Clinical trials testing LAG-3 inhibitors in combination with programmed cell death 1 (PD-1) inhibitors have shown significant improvements in progression-free survival (PFS) compared to PD-1 inhibition alone in patients with melanoma." (PMID 37808404, 2023). "Moreover, LAG-3 and PD-1 have been found to synergistically promote tumoral immune escape in melanoma and colon adenocarcinoma." (PMID 38077396, 2023). "Relatlimab plus nivolumab (anti–lymphocyte-activation gene 3 plus anti–programmed death 1 [anti–LAG-3+anti–PD-1]) has been approved by the FDA as a first-line therapy for stage III/IV melanoma, but its detailed effect on the immune system is unknown." (PMID 36719749, 2023). "In addition, MHC-II+ melanoma tumors have been shown to promote selective adaptive resistance to anti-PD-1 immunotherapy via upregulation of Lag-3 and FCRL664." (PMID 36869048, 2023). "Interestingly, an anti-LAG3 antibody termed Relatlimab was recently demonstrated to be active in combination with nivolumab as a first line treatment of melanoma." (PMID 36975409, 2023). "Importantly, recent trials in melanoma in the neoadjuvant and first-line setting demonstrated the superiority of the combination of anti-LAG3 and anti-PD1 therapy compared to anti-PD1 alone." (PMID 37046760, 2023). "LAG-3 inhibition is an emerging promising immune checkpoint target in melanoma." (PMID 37484526, 2023). "The intensified interest in LAG-3 combination strategies might be due to the persuasive results of the global, randomized, phase 2–3 study (RELATIVITY-047) in melanoma patients that combined the application of relatlimab (anti-LAG-3) and nivolumab (anti-PD-1)." (PMID 37174080, 2023). "In the context of melanoma-infiltrating T cells, the high expression of LAG3 and its interaction with MHC class II molecules may contribute to clonal exhaustion." (PMID 37569880, 2023). "The effects of targeting LAG-3 in melanoma were first reported in an early clinical trial in 2013." (PMID 37670328, 2023). "Overexpression of LAG-3 has been identified on tumor-infiltrating lymphocytes (TILs) in a number of solid tumors, including melanoma, glioma, NSCLC, head and neck squamous cell carcinoma (HNSCC), breast cancer (BC), gastric cancer (GC), and lymphoma, as well as in leukemia." (PMID 37670328, 2023). "It interacts with LAG3 and prevents Teff cell responses in melanoma cells." (PMID 37215135, 2023).